KLF2 (KLF transcription factor 2)
Diseases named in the same sentence as KLF2 in open-access papers (continued):
Sharing a sentence is not in itself a finding about the gene and the disease.
non-small cell lung carcinoma (29 papers, 2015 to 2025). A group of at least three distinct histological types of lung cancer, including non-small cell squamous cell carcinoma, adenocarcinoma, and large cell carcinoma. "There were significant KLF2 down regulations in non small-cell lung cancer (NSCLC) tissues that was correlated with tumor size, tumor stage, lymphatic metastasis, and survival." (PMID 37807067, 2023). "Previous studies indicated that KLF2 significantly suppresses tumor cell viability and induces cell cycle arrest at G0/G1 through up-regulation of p15 and p21 expression in non-small cell lung cancer." (PMID 35033064, 2022). "For instance, Xist acts as an oncogene in non-small cell lung cancer by recruiting EZH2 to the epigenetically repressed kruppel-like factor 2 gene (KLF2)." (PMID 33392092, 2020). "XIST has also been proposed to act as a tumor suppressor in breast cancer by regulating phosphorylated AKT, and as an oncogene in non-small cell lung cancer by downregulating the tumor suppressor KLF2." (PMID 30281678, 2018). "Long noncoding RNA XIST acts as an oncogene in non-small cell lung cancer by epigenetically repressing KLF2 expression." (PMID 30046354, 2018). "XIST acts as an oncogene in non-small cell lung cancer by epigenetically repressing KLF2 expression." (PMID 29371940, 2017). "Further investigation revealed that XIST acts as an oncogene in non-small cell lung cancer by epigenetically repressing KLF2 expression." (PMID 27911852, 2017). "In addition, another study revealed that TIMP/KLF2 is a target of tumor-derived exosomal miR-3157-3p that promotes angiogenesis, vascular permeability, and metastasis in non-small cell lung cancer." (PMID 37234985, 2023). "KLF2 is implicated in regulating adipogenesis, inflammatory diseases such as rheumatoid arthritis and vascular diseases, chronic infections, and malignancies, including ccRCC, endometrial cancer, CRC, non-small cell lung cancer, and pancreatic cancer." (PMID 37123417, 2023). "EZH2 could result in a diminished level of Krüppel-like factor 2 (KLF2) in multiple cancers such as cervical cancer and non-small cell lung cancer." (PMID 34462420, 2021). "EZH2, interacting with lncRNA X-inactive specific transcript, could lead to suppression of KLF2 transcription in non-small cell lung cancer." (PMID 34462420, 2021). "Moreover, XIST mediated oncogenic effects is partially through its epigenetically silencing of KLF2 expression in non-small cell lung cancer." (PMID 29568404, 2018). "In a study of non-small-cell lung cancer, upregulation of SBF2-AS1 and AGAP2-AS1 promoted tumor-cell proliferation by negatively regulating p21, KLF2 and LATS2." (PMID 36673815, 2023). "LINC00511 downregulates LATS2 and KLF2 by combining EZH2 and LSD1 to promote the proliferation, migration, and invasion of non-small-cell lung cancer." (PMID 35664432, 2022). "In non-small cell lung cancer, lncRNA AGAP2-AS1 acts as an oncogene that inhibits the expression of large tumor suppressor kinase 2 (LATS2) and Kruppel-like factor 2 (KLF2) via interacting with EZH2 and LSD1." (PMID 32202509, 2020). "In non-small-cell lung cancer cells, upregulated long non-coding RNA AGAP2-AS1 represses LATS2 and KLF2 expression through interacting with EZH2 and LSD1." (PMID 29050269, 2017). "A recent study indicated that long non-coding RNA LINC01133 repressed KLF2, P21 and E-cadherin transcription through binding with EZH2, LSD1 in non small cell lung cancer." (PMID 29113337, 2017). "For example, lncRNA AGAP2-AS1 has been demonstrated to recruit the enhancers of zeste homolog 2 (EZH2) and LSD1 to the promoter regions of KLF2 and large tumor suppressor 2 (LATS2), thus suppressing the transcription of KLF2 and LATS2 and promoting the progression of non-small cell lung cancer." (PMID 38516191, 2024). "lncRNA AGAP2-AS1 could bind with EZH2 and LSD1 and recruit them to KLF2 and LATS2 promoter regions to repress their transcription in non-small-cell lung cancer." (PMID 30069164, 2018).
non-small cell lung carcinoma (continued). "It was also reported that the upregulation of the long non-coding RNA AGAP2-AS1 facilitates cell proliferation, migration and invasion, and inhibits cell apoptosis; it also represses LATS2 and KLF2 expression through its interaction with EZH2 and LSD1 in non-small-cell lung cancer cells." (PMID 27906682, 2017). "Exosomal miR-3157-3p from non-small cell lung carcinoma (NSCLC) cells promotes pre-metastatic niche formation, angiogenesis, and increased vascular permeability by targeting tissue inhibitor of metalloproteinase (TIMP)/KLF2, which regulates the expression of VEGF, MMP2, MMP9, and occludin in ECs." (PMID 40002766, 2025).
pancreatic cancer (20 papers, 2017 to 2024). "SNHG15 induced pancreatic cancer cell proliferation by repressing P15 and KLF2 expression via EZH2-related H3K27me3." (PMID 37807067, 2023). "IRAIN induced cell proliferation directly through interacting with EZH2 and LSD1 complexes and suppressing KLF2 and P15 in pancreatic cancer cells." (PMID 37807067, 2023). "KLF2 is a known suppressor, and its expression is lost or significantly inhibited in pancreatic cancer tissue compared to adjacent normal tissues." (PMID 37239940, 2023). "DUXAP8 promoted the cell proliferation and tumor progression in pancreatic cancer through p21 and KLF2 down regulations following interaction with EZH2 and LSD1." (PMID 37807067, 2023). "KLF2 inhibited the growth and metastasis of pancreatic cancer cells by interaction with b-catenin that suppressed the activity of b-catenin/TCF complex." (PMID 37807067, 2023). "KLF2 also induced pancreatic tumor cell senescence through cooperating with FOXO4 and promoting the expression of p21." (PMID 37807067, 2023). "To validate the influence of CDKN1A and KLF2 on cellular proliferation of pancreatic cancer cells, we knocked down CDKN1A and KLF2 expression in BxPC-3 cells." (PMID 30367681, 2018). "Next, to further investigate whether CDKN1A and KLF2 are involved in the enhanced cellular proliferation induced by DUXAP8 in pancreatic cancer cells, we performed rescue experiments." (PMID 30367681, 2018). "Furthermore, our findings indicated that lncRNA SNHG15 promoted pancreatic cancer cell proliferation through epigenetic repression of P15 and Kruppel-like factor 2 (KLF2)." (PMID 29137412, 2017). "Overexpression of KLF2 resulted in more nominal growth of organoids, suggesting that it may impair the activity of pancreatic cancer stem cells, and xenografts studies showed that its overexpression reduced the tumorigenicity of pancreatic cancer." (PMID 37239940, 2023). "By downregulating DUXAP8 in lung cancer cells, it is not only possible to inhibit the proliferation of pancreatic cancer cells through silencing CDKN1A and KLF2, but also to induce their apoptosis." (PMID 34431643, 2021). "In pancreatic carcinoma, DUXAP8 promotes tumor growth through epigenetically silencing CDKN1A and KLF2." (PMID 34957112, 2021). "In pancreatic cancer, DUXAP8 enhanced cancer cell proliferation by epigenetically silencing CDKN1A and KLF2." (PMID 32849765, 2020). "In pancreatic cancer, SNHG15 was found to be up-regulated and to suppress the transcription of P15 and KLF2 (Kruppel Like Factor 2) by binding to EZH2 and the subsequent methylation at the promoter region of the histone 3 (H3K27me3)." (PMID 32318335, 2020). "By epigenetically silencing CDKN1A an KLF2, DUXAP8, upregulated in pancreatic cancer, promoted growth of pancreatic cancer." (PMID 32185172, 2020). "qRT-PCR analysis using 20 pairs of pancreatic cancer and adjacent normal tissues showed significantly higher CDKN1A and KLF2 expression in the cancer tissues." (PMID 30367681, 2018). "Additionally, the RNA immunoprecipitation (RIP) assay results revealed that SNHG15 inhibited the expression of P15 and KLF2 through EZH2-mediated H3K27ME3, and promoted the proliferation of pancreatic cancer cells." (PMID 38526609, 2024). "Similarly to KLF2 and KLF3, KLF6 is another tumor suppressor whose levels are inhibited in PDAC tissues and whose overexpression reduces pancreatic cancer proliferation, migration, and invasion." (PMID 37239940, 2023). "DUXAP8 promoted pancreatic cancer cell growth by epigenetically regulating CDKN1A and KLF2." (PMID 35794983, 2022). "This study provides the first direct evidence that DUXAP8 is a critical and powerful regulator of genes involved in pancreatic cancer progression through silencing CDKN1A and KLF2 in the nucleus, indicating that DUXAP8 is a potential therapeutic target of pancreatic cancer." (PMID 30367681, 2018).
pancreatic cancer (continued). "Angiogenesis is further influenced by CDK8, which has been found that when overexpressed, it promotes angiogenesis in pancreatic cancer via activation of CDK8/β-catenin/KLF2 signalling, while silencing of CDK8 inhibits angiogenesis in pancreatic cancer in vitro and in nude mice xenograft models." (PMID 30340359, 2018). "DUXAP8 induced increase in pancreatic cancer cell proliferation and tumorigenesis may be partly mediated via epigenetically silencing CDKN1A and KLF2 transcription by binding with EZH2 and LSD1." (PMID 30367681, 2018).
breast carcinoma (18 papers, 2013 to 2024). "In breast cancer, KLF2 is a diagnostic/prognostic biomarker because it is downregulated in tumor tissues compared with para-carcinoma controls." (PMID 38495481, 2024). "Associations between KLF2 expression levels and clinic-pathologic parameters in breast cancer patients." (PMID 37123417, 2023). "A comprehensive analysis of KLF2 co-expression gene networks in breast cancer was conducted to explore the underlying biological functions and signaling pathways associated with these genes." (PMID 37123417, 2023). "To investigate the underlying mechanism of KLF2 in breast cancer, we performed Gene Set Enrichment Analysis (GSEA) to identify differentially expressed genes." (PMID 37123417, 2023). "Therefore, further experimental validation is necessary to confirm these results and establish the role of KLF2 as a diagnostic marker and potential therapeutic target for breast cancer." (PMID 37123417, 2023). "RUSC1-AS1 promotes the proliferation of breast cancer by inhibiting KLF2 and CDKN1A, which may serve as a potential hallmark for breast cancer." (PMID 32793475, 2020). "Indeed, KLF2 was previously implicated as a tumor suppressor gene in breast cancer." (PMID 38874684, 2024). "As PIM1-3 act as oncogenes and are involved in breast cancer progression, induction of these kinases likely impedes the inhibitory effect of KLF2 induction by UM171." (PMID 38874684, 2024). "While breast cancer inhibitory effect was in part associated with upregulation of P21CIP1 and KLF2, this compound also activated the expression of oncogenes PIM1-PIM3 that likely imped the anti-neoplastic of the compound." (PMID 38874684, 2024). "Mechanistically, KLF2 activates dendritic cells to modulate the immune microenvironment of breast cancer and restrains angiogenesis via downregulating VEGFA and HIF1α expression." (PMID 38495481, 2024). "Accordingly, lentivirus-mediated knockdown of KLF2 in breast cancer cells significantly reduced growth suppression by UM171." (PMID 38874684, 2024). "To verify the clinical significance of KLF2, we analyzed the clinical data from the TCGA breast cancer cohort." (PMID 37123417, 2023). "Consistent with previous studies, we also found that statins promote KLF2 expression in mouse tumor tissues and human breast cancer cells MCF7 and MDA-MB-231." (PMID 37123417, 2023). "The expression levels of KLF2 in breast cancer were validated via immunohistochemical staining analysis." (PMID 37123417, 2023). "In order to investigate the potential role of KLF2 in the clinical management of breast cancer, we conducted an analysis of the GSE63427 dataset obtained from the GEO database." (PMID 37123417, 2023). "We validated the differential expression of KLF2 in breast cancer and normal tissue samples using immunohistochemical (IHC) staining." (PMID 37123417, 2023). "The present study analyzed the correlation between KLF2 expression levels and immune cell infiltration in breast cancer samples using the TIMER database." (PMID 37123417, 2023). "The expression of KLF2 following diverse breast cancer therapies was analyzed in the Gene Expression Omnibus (GEO) databases." (PMID 37123417, 2023). "In the present study, our findings demonstrate that simvastatin treatment significantly enriches the KLF2-positive population of breast cancer cells." (PMID 37123417, 2023). "We observed similar results in 33 pairs of paracancer and breast cancer tissues, but further investigation with a larger sample size is needed to confirm the relationship between KLF2 and ER, PR, and HER2 in clinical tissue samples." (PMID 37123417, 2023). "Furthermore, in breast cancer, we explored the association between KLF2 and diverse immune infiltration cells, angiogenesis, vasculature development, and endothelium development, and DNA double-strand break repair, which may be related to the VEGF-Hif1α pathway." (PMID 37123417, 2023).
breast carcinoma (continued). "In summary, our investigation explored the relationship between KLF2 expression and various pathological features, immune infiltration, angiogenesis, regulatory networks, and therapy in breast cancer using multiple perspectives." (PMID 37123417, 2023). "The relationship between KLF2 expression and clinical features or immune infiltration of The Cancer Genome Atlas (TCGA) breast cancer samples was evaluated using Breast Cancer Integrative Platform (BCIP) and TIMER." (PMID 37123417, 2023). "Our analysis demonstrated that the expression level of KLF2 was significantly reduced in breast cancer compared to the control group." (PMID 37123417, 2023). "Consistent with the database, the expression levels of KLF2/4/6/8/9/11/15 were significantly down-regulated in breast cancer tissues by RT-PCR and IHC." (PMID 35033064, 2022). "It promotes the proliferation of breast cancer cells by epigenetic silence of KLF2 and CDKN1A, and is also involved in hepatocellular carcinoma by modulating Notch signaling through its interaction with miR-7-5p." (PMID 36290414, 2022). "We further cross-analyzed the RFS of patients with breast cancer based on KLF2/4/8/11/15 expression levels for intra-family study." (PMID 35033064, 2022). "Consistent with previous study, we observed that the expression of KLF2/4/6/8/9/11/15 is down-regulated in breast cancer tissues compared to normal breast tissues." (PMID 35033064, 2022). "KLF2 is also downregulated in breast cancer, having a tumor suppressor activity that can control the transcriptional activity of vitamin A metabolite retinoic acid (RA), while its expression positively correlates with patients’ survival." (PMID 36101460, 2022). "The MTT and colony formation assays indicated that overexpression of KLF2 or KLF15 inhibited breast cancer cell proliferation." (PMID 35033064, 2022). "The transwell and scratch assays indicated that overexpression of KLF2 or KLF15 inhibited breast cancer cell migration)." (PMID 35033064, 2022). "Oncogene, LDLRAD4, which was highly expressed in multiple cancers (e.g., hepatic cancer, breast cancer and colon cancer), and KLF2, an essential transcriptional factor for MM cell survival, were also downregulated in all treated cells." (PMID 34571936, 2021). "We show here that KLF2 is markedly downregulated in human breast cancers and that its expression positively correlates with breast cancer patient survival." (PMID 26416422, 2015). "Our analysis of a TissueScanTM human breast cancer cDNA array (OriGene) similarly showed marked downregulation of KLF2 at early stage of breast cancer." (PMID 26416422, 2015). "The data further show that KLF2 is downregulated in early stage and remains low at all stages of breast cancer." (PMID 26416422, 2015). "A xenograft mouse model of breast cancer was used to further examine the involvement of KLF2 in mammary tumor development." (PMID 26416422, 2015). "We analyzed if other BP are also able to modulate KLF2 expression in breast cancer cells and if probenecid can enhance the observed effects." (PMID 25496233, 2014). "Based on our findings, we speculate that KLF2 regulates the activation of dendritic cells, thereby enhancing the function of human T lymphocytes and playing an anti-tumor role in breast cancer." (PMID 37123417, 2023). "Previous reports have highlighted the important role of KLF2 in regulating the tumor immune microenvironment, while immunotherapy represents a significant hope for breast cancer treatment." (PMID 37123417, 2023). "KLF2 is also involved in regulating tumor angiogenesis, and in this study, we found that KLF2 is closely related to angiogenesis and endothelial function in breast cancer." (PMID 37123417, 2023). "Specifically, KLF2 was found to be downregulated in breast cancer and was positively correlated with the expression of ER, PR, HER2, and negatively correlated with pathological grade, pathological stage, tumor size, lymph node metastases, and distant metastasis." (PMID 37123417, 2023).